TNF (tumor necrosis factor)
Description:
Cytokine that binds to TNFRSF1A/TNFR1 and TNFRSF1B/TNFBR. It is mainly secreted by macrophages and can induce cell death of certain tumor cell lines. It is potent pyrogen causing fever by direct action or by stimulation of interleukin-1 secretion and is implicated in the induction of cachexia, Under certain conditions it can stimulate cell proliferation and induce cell differentiation. Impairs regulatory T-cells (Treg) function in individuals with rheumatoid arthritis via FOXP3 dephosphorylation. Up-regulates the expression of protein phosphatase 1 (PP1), which dephosphorylates the key 'Ser-418' residue of FOXP3, thereby inactivating FOXP3 and rendering Treg cells functionally defective. Key mediator of cell death in the anticancer action of BCG-stimulated neutrophils in combination with DIABLO/SMAC mimetic in the RT4v6 bladder cancer cell line. Induces insulin resistance in adipocytes via inhibition of insulin-induced IRS1 tyrosine phosphorylation and insulin-induced glucose uptake. Induces GKAP42 protein degradation in adipocytes which is partially responsible for TNF-induced insulin resistance (By similarity). Plays a role in angiogenesis by inducing VEGF production synergistically with IL1B and IL6. Promotes osteoclastogenesis and therefore mediates bone resorption (By similarity). The TNF intracellular domain (ICD) form induces IL12 production in dendritic cells.
Synonyms: TNFA; TNFSF2; DIF; TNF-alpha; IMD127; TNLG1F
Tractability: Small molecule: a structure with a bound ligand is known; a high-quality ligand is known; it has a high-quality binding pocket; it belongs to a druggable protein family. Antibody: an approved drug acts on it; UniProt places it where antibodies can reach, with high confidence; its Gene Ontology location is reachable by antibodies, with high confidence; UniProt predicts a signal peptide or a membrane-spanning region. PROTAC: a small molecule that binds it is known. Other modalities: an approved drug acts on it.
Target class: Secreted protein
Chemical probes: GANODERIC ACID A, GANODERIC ACID B, GANODERIC ACID C2, GANODERIC ACID D, GANODERIC ACID H, GANODERIOL F
Safety:
Unwanted effects reported when the protein is acted on. In parentheses: how it was acted on, where the effect was seen, and who reports it.
chance of severe hypersensitivity (source: ClinPGx)
chance of severe hypersensitivity to carbamazepine treatment (source: ClinPGx)
hand-foot syndrome (source: ClinPGx)
hypersensitivity (source: ClinPGx)
neuropathy (source: ClinPGx)
thrombocytopenia (source: ClinPGx)
Toxic liver disease (source: ClinPGx)
Gene: Protein-coding gene on chromosome 6 (31,575,565 to 31,578,336, forward strand). Ensembl gene ENSG00000232810.
Subcellular location: Cell membrane; Membrane (Tumor necrosis factor, membrane form); Secreted (Tumor necrosis factor, soluble form); Secreted (C-domain 1); Secreted (C-domain 2)
Pathways (Reactome):
Signal Transduction: Regulation of TNFR1 signaling; TNF signaling; TNFR1-induced NF-kappa-B signaling pathway; TNFR1-induced proapoptotic signaling; TNFR1-mediated ceramide production
Immune System: Interleukin-10 signaling; Interleukin-4 and Interleukin-13 signaling; TNFR2 non-canonical NF-kB pathway
Developmental Biology: Differentiation of naive CD4+ T cells to T helper 1 cells (Th1 cells); Transcriptional regulation of white adipocyte differentiation
Gene Ontology:
Molecular function: cytokine activity; identical protein binding; protease binding; protein binding; transcription cis-regulatory region binding; tumor necrosis factor receptor binding; receptor ligand activity; histone H3K9ac reader activity
Biological process: antiviral innate immune response; cellular response to ionizing radiation; cellular response to nicotine; chronic inflammatory response to antigenic stimulus; embryonic digestive tract development; extrinsic apoptotic signaling pathway; extrinsic apoptotic signaling pathway via death domain receptors; inflammatory response; inflammatory response to wounding; leukocyte tethering or rolling; necroptotic signaling pathway; negative regulation of apoptotic signaling pathway; negative regulation of bicellular tight junction assembly; negative regulation of blood vessel endothelial cell migration; negative regulation of branching involved in lung morphogenesis; negative regulation of cytokine production involved in immune response; negative regulation of DNA-templated transcription; negative regulation of extrinsic apoptotic signaling pathway in absence of ligand; negative regulation of gene expression; negative regulation of interleukin-6 production; negative regulation of lipid catabolic process; negative regulation of transcription by RNA polymerase II; negative regulation of vascular wound healing; negative regulation of viral genome replication; positive regulation of apoptotic process; and 141 more
Cellular component: cell surface; extracellular region; membrane raft; plasma membrane; external side of plasma membrane; phagocytic cup; recycling endosome; membrane; neuronal cell body
Genetic constraint (gnomAD): Loss-of-function variants: 7 observed, 22.2 expected, observed/expected ratio (o/e) 0.32, 90% interval 0.18 to 0.59. The upper end of that interval is the gene's LOEUF score, 0.59, which puts it in group 2 of 6, group 1 being the genes least tolerant of losing a copy. Missense variants: 216 observed, 308.66 expected, observed/expected ratio (o/e) 0.7, 90% interval 0.62 to 0.78. Synonymous variants: 123 observed, 135.93 expected, observed/expected ratio (o/e) 0.9, 90% interval 0.78 to 1.05.
Homologues: Orthologues: macaque TNF (96% identical), chimpanzee TNF (94% identical), dog TNF (91% identical), pig TNF (87% identical), guinea pig TNF (80% identical), rabbit TNF (80% identical), mouse Tnf (79% identical), rat Tnf (79% identical), tropical clawed frog tnf (30% identical). Paralogues in human: TNFSF15 (26% identical), LTA (25% identical), FASLG (22% identical), LTB (22% identical), TNFSF14 (21% identical), CD40LG (19% identical), TNFSF10 (16% identical), TNFSF11 (15% identical).
Diseases named in the same sentence as TNF in open-access papers:
TNF is named in the same sentence as 2,244 diseases in open-access papers, as found by Europe PMC text mining. Sharing a sentence is not in itself a finding about the gene and the disease. The quoted sentences say what the papers report.
Obesity (4,297 papers, 2001 to 2026). Accumulation of substantial excess body fat. "In our analysis of inflammatory cytokine levels, we found that CCPP intervention reduced the concentrations of pro-inflammatory factors (TNF-α, IL-1β, and IL-6) and alleviated inflammatory responses associated with obesity development." (PMID 41596915, 2026). "For instance, pro-inflammatory cytokines like interleukin-6 (IL-6) and tumor necrosis factor-alpha (TNF-α) are elevated in obesity and have been associated with insulin resistance and beta-cell dysfunction." (PMID 40804870, 2025). "Applying qRT-PCR, we also detected increase expression of the cytokines IL-6, IL-8, and TNFα, key players in the obesity-associated BC progression in tumors grown under ME conditions." (PMID 40868123, 2025). "TNF‐α release from adipose tissue macrophages is a characteristic feature of obesity‐related chronic inflammation and has been implicated in the pathogenesis of insulin resistance and metabolic syndrome." (PMID 40129260, 2025). "Obesity is associated with elevated levels of IL-6, TNF-α, CRP, and leptin, as well as altered macrophage profiles - all of which contribute to systemic and neural inflammation." (PMID 40909065, 2025). "Linked with immunological disorders.Diabetes: High blood sugar affects neutrophil activity and T cell responses, increasing the infection risk.Obesity causes low-grade inflammation from higher pro-inflammatory cytokines (IL-6, TNF-α)." (PMID 40364844, 2025). "CCL2 mediates monocyte recruitment, M1 polarization and the upregulation of TNF-α and IL-6 in fat pads, contributing to the inflammatory milieu linked to obesity-associated comorbidities." (PMID 40328980, 2025). "Obesity is linked to an increase in inflammatory cytokines, such as interleukin-6 (IL-6), IL-18, and tumor necrosis factor alpha (TNF-α), which are believed to play a role in HS and AC." (PMID 40969999, 2025). "This systematic review and meta‐analysis were performed to analyze the effect of achieving weight loss through dietary interventions on serum IL‐6 and TNF‐α in adults with obesity with at least 12 months' follow‐up." (PMID 40090867, 2025). "In general, obesity and insulin resistance are associated with increased proinflammatory cytokines from the adipose, including leptin, IL-6, TNFα, and resistin." (PMID 40985048, 2025). "The correlation between leptin and TNF-α is known to be associated with inflammatory diseases such as sepsis, psoriasis, preeclampsia, and obesity." (PMID 41153693, 2025). "MCP-1 and TNF-α play crucial roles in the relatively early stages of inflammation associated with obesity, whereas IL-6 and IL-1β are potentially involved in the later phases of inflammation." (PMID 39803918, 2025). "Adipose tissue also produces a variety of adipokines and proinflammatory cytokines linked to obesity-associated male infertility, including leptin, adiponectin, resistin, ghrelin, TNF-alpha, IL-1β and IL-6." (PMID 40140188, 2025). "Since obesity is associated with low-grade inflammation, we determined blood concentrations of IL-6 and TNF-α by ELISA." (PMID 40284173, 2025). "Among the genetic factors, specific genes involved in inflammatory and oxidative processes, such as tumor necrosis factor-alpha (TNF-α), have been implicated in the development of obesity and insulin resistance." (PMID 40732969, 2025). "TNF-α is an important and effective pro-inflammatory adipocytokine that is involved in causing low-grade inflammation and influencing CVDs involving OW/obesity, atherosclerosis and other disorders." (PMID 39982363, 2025). "Obesity is linked with low-grade inflammation, which includes the release of tumor necrosis factor-α (TNF-α) from macrophages and adipocytes." (PMID 40228714, 2025). "Since resistin is elevated in obesity, it is thought that, throughout the impact on TNF-α and IL-6, resistin can, to a certain extent, explain the association between obesity and the severity of psoriasis." (PMID 40277935, 2025).
Obesity (continued). "Obesity is also linked to subclinical chronic inflammation, characterised by the release of pro-inflammatory proteins into the circulation, including IL-6, TNF α, interleukin 8 (IL-8), and high-sensitivity C-reactive protein (C-RP hs)." (PMID 40310144, 2025). "On meta-regression, obesity was associated with increased risk of MACEs with JAK inhibitors vs TNF antagonists (eTable 4 in Supplement 1)." (PMID 40928778, 2025). "Among these, tumor necrosis factor-alpha (TNF-α), a pro-inflammatory cytokine secreted by macrophages and monocytes, is closely linked to obesity-related inflammation." (PMID 40970779, 2025). "Its expression is markedly increased in individuals with obesity and type 2 diabetes, where it shows a positive association with both glycated hemoglobin (HbA1c) levels and inflammatory biomarkers like TNF-α." (PMID 40699839, 2025). "Chronic low-grade inflammation is a defining feature of obesity, and high levels of TNF-α and CRP are caused by several reasons, including immunological activation, metabolic abnormalities, and dysfunctional adipose tissue." (PMID 40700071, 2025). "As an acute-phase reactant to inflammation and infection, C-reactive protein (CRP) is associated with obesity along with inflammatory mediators such as TNF-α and IL-6." (PMID 40939575, 2025). "For patients with high-risk factors such as advanced age, obesity, and hereditary thrombophilia, priority should be given to choosing TNF - α inhibitors with a better thrombotic risk profile (such as infliximab rather than traditional adalimumab)." (PMID 40351429, 2025). "TNF-α is involved in various aspects of the pathophysiological processes underlying obesity, diabetes, and CVDs." (PMID 40699839, 2025). "IF is an effective weight loss strategy, and our findings confirm a reduction in TNF-α, which is in alignment with previous meta-analyses on people with overweight and obesity and in the general adult population." (PMID 40805975, 2025). "The aging process is associated with higher concentrations of TNF-α and other proinflammatory cytokines, while obesity can similarly promote chronic low-grade inflammation in addition to activating T cells, mast cells, and macrophages." (PMID 40629651, 2025). "In white adipose tissue, expansion associated with obesity results in the secretion of adipokine such as TNF-α and IL-6, which recruit and activate macrophages, perpetuating inflammation." (PMID 41415265, 2025). "Elevated TNF-α, associated with obesity and insulin resistance, suppresses the tissue-repair function of skin γδ T cells, whereas TNF-α blockade restores their epithelial responsiveness." (PMID 41341586, 2025). "Obesity is accompanied by elevated levels of pro-inflammatory cytokines such as TNF-α and IL-6, both of which are closely associated with insulin resistance and metabolic disorders, as well as diminished immune cell activity." (PMID 41460779, 2025). "This interaction highlights the potential of antioxidant-rich diets to alleviate insulin resistance, particularly in individuals with obesity carrying the genetic risk variant that increases TNF-α expression." (PMID 40732969, 2025). "In our results, the FAAH rs324420 SNP was positively associated with TNFα levels (p = 0.039), in line with other studies where this SNP has been associated with increased BMI and obesity, as well as markers of systemic inflammation, such as TNFα levels." (PMID 40431452, 2025). "Other inflammatory markers, such as tumor necrosis factor, interleukin-1, and interleukin-6, have also been shown to contribute to an increased risk of obesity." (PMID 40077689, 2025). "First, obesity is associated with a state of chronic low-grade systemic inflammation, characterized by elevated levels of pro-inflammatory cytokines, including tumor necrosis factor-alpha (TNF-α), interleukin-6 (IL-6), C-reactive protein (CRP), and resistin." (PMID 40426647, 2025).
Obesity (continued). "Clinical studies have shown that elevated systemic levels of TNFα as well as overexpression of TNFα in adipose tissue are associated with obesity, insulin resistance, and T2D." (PMID 39269560, 2025). "TNF-α is one of the key mediators of obesity-associated inflammation and can inhibit insulin signaling by activating the JNK/NF-κB pathways, impairing insulin receptor phosphorylation, and contributing to hepatic lipotoxicity." (PMID 40862455, 2025). "The elevated TNF-α that was associated with insulin resistance has been demonstrated in diverse animal obesity models; it was reported that TNF-α was found to promote insulin resistance." (PMID 39762333, 2025). "Certain gene polymorphisms (eg, in TNF-α, IL-6, or muscle growth regulators such as myostatin) have been implicated in sarcopenia and obesity separately." (PMID 40718355, 2025). "Studies demonstrated that abnormalities in microRNA expression, including miRNA 34a, 122, and 192, were associated with unhealthy phenotypes and obesity-associated inflammation markers such as TNFα, IL-1Ra, adiponectin, and procalcitonin." (PMID 40662170, 2025). "Biomarkers such as leptin, adiponectin, and certain inflammatory cytokines (e.g., IL‐6 and TNF‐α) have shown promise in predicting the risk of obesity and its associated complications." (PMID 40551726, 2025). "IL-6 and TNF-α are cornerstone pro-inflammatory cytokines that are elevated in obesity and autoimmune diseases and are directly implicated in prostate cancer pathogenesis." (PMID 41555998, 2025). "Among other functions, it is worth pointing out adiponectin-mediated, i.e., obesity-associated, support of chronic inflammation increases concentrations of tumor necrosis factor alpha (TNF-a) and the interleukin family (IL-6 and IL-18)." (PMID 40559437, 2025). "The results of logistic regression analysis showed that obesity alone and type 2 diabetes with obesity were significantly associated with serum levels of TNF-α, IL-6, leptin, adiponectin, resistin, and ALR after adjusting for sex or age." (PMID 40095937, 2025). "Obesity-related DN is closely associated with chronic, low-grade inflammation and cytokine expression (IL-1α, IL-6, TGFβ, and TNFα), leading to leukocyte recruitment and DN." (PMID 41369384, 2025). "Interleukin‐6 (IL‐6) and tumor necrotic factor‐alpha (TNF‐α) are two cytokines associated with obesity and risk factors for adverse health." (PMID 40243109, 2025). "In LCN2-deficient KO mice, lipocalin-2 deficiency protects mice from developing aging- and obesity-induced insulin resistance largely by modulating 12-lipoxygenase and TNF levels in adipose tissue." (PMID 41227378, 2025). "It is known that TNF-α is elevated in individuals with obesity, and weight loss has been shown to reduce TNF-α concentrations." (PMID 40125475, 2025). "Obesity is associated with increasedsecretion of pro-inflammatory cytokines, thus we evaluated the expressionlevels of the inflammatory markers IL-6, TNF-α, and MCP-1 inboth subcutaneous and visceral fat tissues." (PMID 39895065, 2025). "Adipocytokines such as TNF-α, IL-6, and adiponectin play pivotal roles in mediating insulin resistance and linking obesity to increased cardiovascular risk." (PMID 41008514, 2025). "Obesity, often associated with metabolic syndrome, promotes the production of cytokines such as tumor necrosis factor-alpha (TNF-α), IL-1β, and IL-6, further contributing to AS." (PMID 41458991, 2025). "Background/Objectives: Obesity is associated with chronic systemic inflammation and elevated levels of inflammatory cytokines such as tumor necrosis factor alpha (TNF-alpha), interleukin-6 (IL-6), and C-reactive protein (CRP)." (PMID 40218888, 2025). "Chronic low-grade inflammation (CLGI), characterized by the persistent elevation of pro-inflammatory mediators such as CRP, IL-6, and TNF-α, is a defining feature of obesity-associated PCOS." (PMID 41239503, 2025).